TSSK3 (testis specific serine kinase 3)
Description:
Serine/threonine protein kinase required for spermatid development and male fertility.
Synonyms: SPOGA3; STK22C; STK22D; TSK3
Tractability: Small molecule: a high-quality ligand is known; it belongs to a druggable protein family. PROTAC: ubiquitination databases record sites on it; a small molecule that binds it is known.
Target class: CAMK protein kinase TSSK family; CAMK protein kinase group; Protein Kinase; Enzyme; Kinase
Gene: Protein-coding gene on chromosome 1 (32,351,521 to 32,364,312, forward strand). Ensembl gene ENSG00000162526.
Subcellular location: Cell projection, cilium, flagellum
Subcellular location (Human Protein Atlas): Nucleoli; Nucleoplasm; Nuclear bodies
Gene Ontology:
Molecular function: protein binding; protein serine kinase activity; protein serine/threonine kinase activity; ATP binding; magnesium ion binding; manganese ion binding; protein kinase activity
Biological process: spermatid development; spermatogenesis
Cellular component: sperm flagellum; motile cilium
Genetic constraint (gnomAD): Loss-of-function variants: 16 observed, 19.85 expected, observed/expected ratio (o/e) 0.81, 90% interval 0.55 to 1.22. The upper end of that interval is the gene's LOEUF score, 1.22, which puts it in group 5 of 6, group 1 being the genes least tolerant of losing a copy. Missense variants: 345 observed, 356.65 expected, observed/expected ratio (o/e) 0.97, 90% interval 0.88 to 1.06. Synonymous variants: 146 observed, 140.95 expected, observed/expected ratio (o/e) 1.04, 90% interval 0.9 to 1.19.
Homologues: Orthologues: chimpanzee TSSK3 (99% identical), macaque TSSK3 (99% identical), mouse Tssk3 (98% identical), dog TSSK3 (97% identical), rat Tssk3 (97% identical), rabbit TSSK3 (97% identical), pig TSSK3 (97% identical), guinea pig TSSK3 (93% identical), Caenorhabditis elegans C27D6.11 (38% identical), Caenorhabditis elegans Y38H8A.4 (37% identical), Caenorhabditis elegans tag-344 (37% identical), Drosophila melanogaster Snrk (35% identical), and 3 more. Paralogues in human: TSSK6 (48% identical), TSSK1B (47% identical), TSSK2 (47% identical), TSSK4 (41% identical), NUAK1 (38% identical), SIK2 (38% identical), NUAK2 (37% identical), SNRK (37% identical), HUNK (37% identical), MELK (37% identical), SIK1 (37% identical), SIK3 (36% identical), and 5 more.
Diseases named in the same sentence as TSSK3 in open-access papers:
TSSK3 is named in the same sentence as 3 diseases in open-access papers, as found by Europe PMC text mining. Sharing a sentence is not in itself a finding about the gene and the disease. The quoted sentences say what the papers report.
Infertility (1 paper, 2024). "TSSK3 is crucial for phosphorylation of multiple infertility-related proteins and plays an essential role in spermiogenesis." (PMID 38714941, 2024).
cancer (1 paper, 2023). A tumor composed of atypical neoplastic, often pleomorphic cells that invade other tissues. "In addition, members of the TSSK family such as TSSK2, TSSK3, and TSSK6 play important roles in survival and proliferation of cancer cells, and TSSK6 is an immunogenic cancer/testis antigen in various cancers." (PMID 37149634, 2023).
TSSK3 also shares sentences with these, for which no sentence is quoted: male infertility (1 paper).